ALB (albumin)
Diseases named in the same sentence as ALB in open-access papers (continued):
Sharing a sentence is not in itself a finding about the gene and the disease.
malnutrition (continued). "In addition, malnutrition is associated with poor outcomes in intensive care unit patients (ICU); albumin may reflect the nutritional state of critically ill patients and a low level of serum albumin may be associated with a malnutritional state in these patients." (PMID 36079002, 2022). "In our study, patients with an AoAC score >2 also were significantly older; had lower serum albumin, low serum hemoglobin and TSAT levels; and elevated serum PTH levels because of malnutrition, inflammation, and atherosclerosis syndrome." (PMID 36561768, 2022). "The 59.4% of the patients (19 out of 32) had a pre-albumin level below 10 mg/dL threshold at the ICU admission, as a possible sign of pre-existent state of malnutrition." (PMID 35276795, 2022). "Furthermore, given that albumin is the primary carrier protein for circulating zinc, measured zinc concentrations may not reflect actual status in some populations such as those with acute illness or malnutrition." (PMID 35689131, 2022). "This 12-week, randomized, single-blind clinical trial with C. butyricum enrolled a cohort of long-term care subjects in a community hospital (aged 83.2 ± 5.3) suffering from malnutrition (MNA-SF score ≤ 7, average albumin 36.38 ± 2.98 g/L)." (PMID 36079806, 2022). "Albumin, a component of the CONUT score, has traditionally been used as an indicator of malnutrition or a predictor of mortality in patients with CKD." (PMID 35684116, 2022). "The relationship between malnutrition status assessed using the MNA and serum albumin levels and outcomes was analyzed using multilevel multiple logistic regression." (PMID 36687683, 2022). "A few studies have investigated the role of albumin as a biomarker associated with the severity of SSc, and these were mainly interested in the prevalence of and potential association with malnutrition (whether or not taking albuminemia into account) in SSc patients." (PMID 36079017, 2022). "There was a positive correlation between malnutrition based on GLIM criteria, serum albumin, and CRP." (PMID 35276861, 2022). "Malnutrition is highly prevalent in CKD patients, especially among patients on dialysis, which leads to low albumin levels." (PMID 35572991, 2022). "The GLIM established a consensus for the identification and endorsement of criteria for the diagnosis of malnutrition in clinical settings including supportive proxy measures of inflammation, such as CRP, albumin, or pre-albumin." (PMID 35807934, 2022). "To assess the prognostic utility of malnutrition assessed by the MNA and serum albumin levels, we conducted a Kaplan–Meier analysis." (PMID 36687683, 2022). "The prevalence of malnutrition based on the MNA criteria (MNA < 17 points) was 18.2%, and 13.1% based on serum albumin concentration (<3 g/dl).The MNA had an overall Internal consistency of Cronbach’s alpha 0.61." (PMID 36411835, 2022). "They show that MIS that includes 7 SGA components and TIBC, albumin and BMI, and GNRI is superior over SGA in malnutrition evaluation." (PMID 35252294, 2022). "The GNRI is composed of serum albumin levels and body weight (actual body weight [ABW]/IBW) and represents malnutrition." (PMID 35256659, 2022). "Weinsier constructed a likelihood of malnutrition score (LOM) score based on the following: body weight, tricep skinfold thickness, and mid-arm circumference, serum folate, vitamin C and serum albumin, and absolute lymphocyte count and hematocrit." (PMID 34868791, 2021). "In general, males and females were equally distributed, 60% of the patients had some degree of malnutrition according to SGA, and the mean serum albumin was below 3.8 mg/dL." (PMID 32860211, 2021). "For example, IP10 and TNFα correlated with the albumin/globulin ratio (i.e., AGR) and a low AGR can be indicative of infection, liver disease, or malnutrition." (PMID 34067023, 2021). "Our study reveals significant associations between nutritional status (as assessed by SGA dialysis malnutrition score) and BMI, MUAC, and albumin." (PMID 34123420, 2021).
malnutrition (continued). "Furthermore, serum albumin concentration was significantly lower in lung cancer patients than in control subjects (3.86 vs. 4.27 g/dL), and significantly more lung cancer patients than control subjects had albumin concentrations <3.5 g/dL (18.2 vs. 4.0%) indicating malnutrition." (PMID 34832849, 2021). "In fact, serum albumin, CRP, IL-6, and fetuin seem to be predictors of malnutrition, cardiovascular disease, and mortality in patients with advanced CKD." (PMID 34063052, 2021). "Interestingly, higher albumin was also identified as an indicator of superior survival, which suggested that cancer-related malnutrition may facilitate the phenomenon of activated systemic inflammatory reactions and immunocompromised host, yielding a poor prognosis." (PMID 34692490, 2021). "Serum albumin (ALB) is commonly used as an indicator of nutritional status and reflects the degree of malnutrition." (PMID 34414685, 2021). "Serological tests showed that the levels of serum albumin (ALB) and prealbumin (PA) were significantly reduced in DMD-delE51 pigs, indicating malnutrition." (PMID 34266495, 2021). "Inconsistency was noted between FFMI and albumin, FFMI and NRS 2002, FFMI and PG-SGA in the assessment of malnutrition (P = 0.132, 0.219, and 0.501, separately)." (PMID 33763439, 2021). "Previous studies 32-34 have explored the prognostic factors for short-term all-cause mortality in elderly patients with HD include lower serum albumin, lower BMI, higher level of C-reactive protein (CRP), suboptimal initiation of HD, malnutrition and frailty." (PMID 34400900, 2021). "GRIm-Score is composed of both inflammatory and nutritional conditions by effectively incorporating LDH, ALB, and NLR, all of which have been widely explored to reflect systemic inflammation and malnutrition of CRC patients." (PMID 34917499, 2021). "PNI, which is defined according to the combined parameters of albumin and lymphocytes, may be particularly useful due to its role as a surrogate marker of both inflammation and nutritional status, thus reflecting the presence of both acute inflammation and malnutrition." (PMID 34298811, 2021). "Serum albumin (ALB) is generally recognized as an indicator of nutrition, and low ALB levels often indicate malnutrition." (PMID 32655630, 2020). "Malnutrition preceded CUA onset, with a median albumin decrease of 2.7 g/L within the 6 months before onset and C-reactive protein (CRP) was high at both times." (PMID 32101140, 2020). "Our findings support the importance of plasma albumin measure and potential benefit of boosting plasma levels of albumin in SCD, especially in SCD endemic countries with high frequency of protein-calorie malnutrition." (PMID 32776978, 2020). "Serum proteins such as albumin and transferrin are classic markers for PEM, and have been considered major indicators of malnutrition." (PMID 33256142, 2020). "Findings called into question the values of serum albumin level and TLC as a surrogate of malnutrition for predicting wound complications after TKA." (PMID 33939393, 2020). "The present meta-analysis indicated that L-carnitine can have a favorable effect on malnutrition biomarkers in patients on MHD, including the increase in albumin, total protein, transferrin, and prealbumin levels." (PMID 32490516, 2020). "HD patients with catheter access compared to fistula and graft had significantly higher malnutrition–inflammation score (MIS) and lower serum albumin levels." (PMID 33076282, 2020). "In conclusion, the present meta-analysis indicated that L-carnitine has a favorable effect on malnutrition biomarkers in patients on MHD, including the increase in the levels of albumin, total protein, transferrin, and prealbumin." (PMID 32490516, 2020). "The GPS, which takes into account albumin and CRP level values, showed that nearly 36% of patients had some degree of malnutrition or inflammation." (PMID 31583040, 2019).
malnutrition (continued). "Integrating comprehensive clinical assessment, anthropometric measurements and objective biochemical analyses such as albumin and conjugated bilirubin is essential for evaluation, follow-up and management of CLD children with variable degree of malnutrition." (PMID 31864303, 2019). "Serum albumin was significantly lower, and the SGA indicated malnutrition (SGA B or C) significantly more often in the sarcopenic group (p < 0.01 each)." (PMID 31601040, 2019). "Levels of albumin and prealbumin in patients with MNA-SF <12 and malnutrition confirmed by biochemical parameters (n = 29) according to gender and MNA-SF score (mean±s.d)." (PMID 29922604, 2018). "Our data also showed that malnutrition induced by NEAA-Ex diet led to a rapid decrease of circulating proteins such as hemoglobin and albumin, whereas the NEAA-R diet decreased only albumin." (PMID 29868589, 2018). "Significant negative correlations of cirrhosis severity were established with BMI, albumin, creatinine, cholesterol, LDL, TG, HDL, hemoglobin, sodium and magnesium indicative of malnutrition." (PMID 29643898, 2018). "Normal nutrition group had significantly higher albumin and leptin levels as well as GNRI than the malnutrition group." (PMID 30089153, 2018). "The current study found prealbumin in HIV-helminth coinfection to be a possible delineator between inflammation-induced reduction and true malnutrition, since in all cases of elevated CRP it remained higher, whereas albumin was lower." (PMID 30065944, 2018). "The reduction on albumin and prealbumin levels were more significant when GNRI was used as the assessment tool for malnutrition, with a more than 10% of decline observed by including patients with acute disease." (PMID 28771192, 2017). "Case mix and malnutrition/inflammation markers, including WBC counts and albumin levels were adjusted." (PMID 27927204, 2016). "The prevalence of malnutrition classified by MNA-SF, NRS2002, BMI, serum albumin, hemoglobin, total lymphocyte count, handgrip strength, calf circumference and mid-arm circumference were 45 %, 38 %, 17 %, 22 %, 24 %, 71 %, 36 %, 12 % and 15 %, respectively." (PMID 26170020, 2015). "Albumin and CRP, both strongly related to inflammation-malnutrition, were shown to be poor predictors of malnutrition in this study." (PMID 27347538, 2015). "However, despite the significant loss of total weight observed in this study after the procedure, an undesirable loss of fat-free mass (about 20%) was observed six months after the surgery which may reflect a problem of malnutrition, represented by serum albumin levels lower than 3.5." (PMID 24523649, 2014). "Low serum albumin has also been found to occur with a variety of acute and chronic diseases and thus is associated with higher mortality in a number of different populations in pathways that may not solely result from malnutrition." (PMID 22532840, 2012). "Malnutrition and low QOL were found to predict prolonged LOS independent of patients' age at diagnosis, surgical approach (laparoscopy or laparotomy), albumin and hemoglobin and suspected clinical diagnosis." (PMID 20497581, 2010). "However, serum albumin concentrations may be influenced by malnutrition, hydration status and trans-capillary escape, as well as the presence of an inflammatory response, and therefore serum CRP concentrations were chosen for entry into the multivariate analysis." (PMID 19127266, 2009). "Albumin (ALB) levels were also lower in the progression group (34.8 ± 5.2 g/L) than the non-progression group (39.1 ± 5.6 g/L), showing a higher incidence of malnutrition." (PMID 41598767, 2026). "SHAP analysis highlighted minimum serum albumin, admission weight, early hypokalemia, and specific ICU admission types as key nonlinear predictors of malnutrition risk." (PMID 42234843, 2026).
malnutrition (continued). "The results indicate that decreased levels of albumin (<3 g/dL) and hemoglobin (<11 g/dL), along with elevated homocysteine, CRP, IL-6 (>7.5 pg/mL), and IP-10 (>250 pg/mL), should alert medical professionals to potential malnutrition in hospitalized patients." (PMID 40094974, 2025). "Although, out of the scope of this study, in the future, if an association between malnutrition and outcomes among SPK recipients is to be sought, should include various other nutritional tools and should not solely rely on the serum albumin levels." (PMID 39906535, 2025). "In parallel, gastric cancer often lowers albumin through a tumor-driven negative acute-phase response, cancer-related malnutrition, and cachexia." (PMID 41210883, 2025). "The serum albumin concentration is not only the most widely used marker of nutritional status but also reflects the negative impact of malnutrition on protein synthesis." (PMID 40094974, 2025). "Similarly, albumin levels, an indicator of nutritional status, often decrease in CHF due to malnutrition and chronic inflammation." (PMID 41012833, 2025). "Traditional biochemical markers of malnutrition, including low albumin, prealbumin, or cholesterol levels, were not present in this cohort." (PMID 41515193, 2025). "It has been reported that nearly 50% of orthopedic patients suffer from malnutrition before surgery, so we assessed whether malnutrition-evaluating markers (PLT, WBC count, LCT, HGB, albumin, and PNI) can predict the failure of PRABCSI in PJI treatment." (PMID 41488484, 2025). "Still, pre-albumin and albumin levels should not be considered valid tools for malnutrition diagnosis, as they are influenced by multiple factors including inflammation and fluid status." (PMID 39906535, 2025). "In October 2020, the American Society for Parenteral and Enteral Nutrition (ASPEN) published a position paper stating that albumin and prealbumin are not components of any accepted definitions of malnutrition." (PMID 39906535, 2025). "Our findings must thus not be misinterpreted as evidence that malnutrition lacks prognostic relevance, but rather that albumin alone is an insufficient surrogate for nutritional status in critically ill COPD patients." (PMID 41010314, 2025). "An analysis of other clinical characteristics showed that stage III-IV patients had markedly abnormal levels of albumin, hemoglobin (Hb), β2-microglobulin (BMG), and lactate dehydrogenase (LDH), indicating malnutrition, severe anemia, and an increased tumor burden in advanced-stage patients." (PMID 40260255, 2025). "Using albumin and BMI to assess nutritional status, we found no severe malnutrition in our patient cohort, which is in contrast to previous studies where malnutrition rates in RPS patients were as high as 46–52%." (PMID 39841283, 2025). "This stands in contrast to the fibrinogen-to-albumin ratio, which predicted cavitary disease severity in Chinese cohorts, possibly because hypo-albuminaemia introduces a malnutrition component absent from CFI." (PMID 40731867, 2025). "As a composite index integrating RDW and albumin, RAR may comprehensively reflect the multifaceted nature of sepsis, including systemic inflammation, oxidative stress, impaired erythropoiesis, and malnutrition." (PMID 40964688, 2025). "However, using body weight and serum albumin, GNRI has been evaluated as a simple and accurate method for assessing malnutrition." (PMID 40069532, 2025). "Amongst 370 patients analyzed, comprising 219 with primary disease, we observed neither a significant prevalence of preoperative malnutrition nor notable changes in BMI or serum albumin levels throughout the disease course." (PMID 39841283, 2025). "Serum albumin level alone is not sufficient to diagnose malnutrition; the GLIM (Global Leadership Initiative on Malnutrition) approach recommends meeting both phenotypic (weight loss, low BMI) and etiological (undernutrition, inflammation) criteria." (PMID 41373357, 2025).
malnutrition (continued). "Patients with low admission albumin (indicating possible malnutrition or severity) did not have significantly longer stays than those with normal or high albumin, nor did patients with extreme hyperalbuminemia exhibit shorter stays." (PMID 41226896, 2025). "Even though it was thought that a low serum albumin level was related to inflammation rather than malnutrition among HD patients." (PMID 39854402, 2025). "Moreover, lower albumin, hemoglobin, phosphate, TIBC, and elevated ferritin suggest a biochemical imbalance accompanying malnutrition, potentially deteriorating their overall health state." (PMID 39854402, 2025). "During the intervention period, all biomarkers remained within the normal range, with albumin (ALB) exceeding 35 g/L indicating the absence of malnutrition, therefore the intervention in this study was safe." (PMID 40216877, 2025). "One is the use of albumin levels as an indicator of nutritional status, which can be modified by factors not directly related to malnutrition, such as inflammation and hydration." (PMID 40077630, 2025). "Low albumin levels were related to poor outcomes in patients with malignant diseases, reflecting both malnutrition and inflammation; it is worth noting that pro-inflammatory cytokines like interleukin 6 (IL-6) and tumour necrosis factor alpha (TNF-α) decrease albumin synthesis." (PMID 41228489, 2025). "ALB, a negative acute phase reactant, decreased during intestinal inflammation, attributing to malnutrition and malabsorption." (PMID 40630487, 2025). "Moreover, malnutrition significantly correlated with increased hospital stay as classified by NRI, albumin, prealbumin, and the ECM/BCM index." (PMID 38339372, 2024). "According with this, there are no data regarding the possible long-term prognostic role of albumin in the younger population with chronic HF, especially in patients without malnutrition." (PMID 38776047, 2024). "Reduced albumin and pre-albumin levels should not be considered a sign of malnutrition in the presence of an acute response (e.g., elevated CRP) when they serve as negative markers of acute response." (PMID 39308920, 2024). "Numerous studies have identified RBC, HGB, ALB, and PAB as significant indicators of malnutrition." (PMID 39664913, 2024). "It should also be noted that patients undergoing elective orthopaedic procedures benefit from protein supplementation even if albumin levels are considered to be within a normal range and no concerns about malnutrition are present." (PMID 38731106, 2024). "We found a significant increase in serum GDF15 levels in AECOPD patients with malnutrition, which was negatively correlated with nutritional indicators such as BMI, MAC, CC, TP, ALB, and PNI, while demonstrating a positive correlation with the inflammatory marker CRP." (PMID 39050134, 2024). "Hypoalbuminemia is common in heart failure (HF) patients; however, there are no data regarding the possible long-term prognostic role of serum albumin (SA) in the younger population with chronic HF without malnutrition." (PMID 38776047, 2024). "It has been shown that reduced serum albumin in dialysis patients can be regarded as a sign of chronic inflammation rather than malnutrition, so the marked hypoalbuminemia in the HD group can be viewed as a sign of a more inflammatory burden in that group." (PMID 39411605, 2024). "In multivariate analysis, except for GLIM-defined malnutrition (p < 0.001), age (p = 0.001), TNM stage (p = 0.001), handgrip strength (p = 0.028), and serum albumin level (p = 0.042) were identified as independent prognostic factors for OS in patients who underwent radical colectomy or proctectomy." (PMID 39502874, 2024). "While BMI and albumin, key indicators of nutritional status, are recognized clinical markers for assessing malnutrition in IPF patients, their significance has not been fully appreciated." (PMID 39407934, 2024).